ADORA2A (adenosine A2a receptor)
Diseases named in the same sentence as ADORA2A in open-access papers (continued):
Sharing a sentence is not in itself a finding about the gene and the disease.
metastatic disease (1 paper, 2024). "Patients with high ADORA2A transcript expression in their tumors had longer OS (from the time of advanced/metastatic disease) compared to those with low/moderate ADORA2A expression (HR 0.69 (95% CI, 0.51–0.95), (p = 0.02))." (PMID 38731962, 2024). "However, high versus not-high ADORA2A transcript expression correlated with longer OS from the time of advanced/metastatic disease (N = 489 patients; (HR 0.69 (95% CI 0.51–0.95) (p = 0.02))." (PMID 38731962, 2024).
neuroendocrine tumors (1 paper, 2024). "For instance, while 73.3% of neuroendocrine tumors expressed high ADORA2A, 26.7% expressed low/moderate ADORA2A." (PMID 38731962, 2024).
osteosarcoma (1 paper, 2020). A usually aggressive malignant bone-forming mesenchymal neoplasm, predominantly affecting adolescents and young adults. "The adenosine A2A receptor is closely related to bone metabolism, and their agonists inhibit osteoclast function, reducing bone destruction in osteosarcoma patients." (PMID 32382539, 2020).
parathyroid adenomas (1 paper, 2013). "We detected both ADORA1 and ADORA2A at the protein level in normal parathyroid and parathyroid adenomas." (PMID 23788688, 2013). "The expression of ADORA1, ADORA2A, and PTH after 30-minute caffeine treatment of cultured parathyroid adenoma cells was evaluated by qRT-PCR." (PMID 23788688, 2013). "ADORA1 showed an equal expression in normal and parathyroid adenomas, whereas ADORA2A was found to be weak or absent in some parathyroid adenoma samples." (PMID 23788688, 2013).
pyelonephritis (1 paper, 2022). An inflammatory process affecting the kidney. "Signaling via adenosine receptors, ADORA2A or ADORA2B, stimulates proton secretion by α‐ICs; thus adenosine production in pyelonephritis‐induced tissue injury may trigger dysregulated urine acidification leading to systemic alkalosis as is the case in GPR116 or ADGRF5‐deficient mice." (PMID 36151614, 2022).
Tics (1 paper, 2015). Repeated, individually recognizable, intermittent movements or movement fragments that are almost always briefly suppressible and are usually associated with awareness of an urge to perform the movement. "We hypothesize that the functional imbalance between the direct and indirect pathways dependent on the activity of adenosine receptors due to abnormal expression of ADORA1 and ADORA2A genes could be responsible for the appearance of tics." (PMID 26317759, 2015).
tongue squamous cell carcinoma (1 paper, 2017). A squamous cell carcinoma that arises from the tongue. "At the first time, we examined the mRNA level of ADORA2A, encoding human A2AR, in Estilo’s tongue squamous cell carcinoma (SCC) dataset, a publicly available cancer database." (PMID 28592285, 2017).
varicocele (1 paper, 2021). A condition characterized by the dilated tortuous veins of the spermatic cord with a marked left-sided predominance. "Polydeoxyribonucleotide (PDRN) is the active fraction extracted from trout spermatozoa and, through stimulation of adenosine A2A receptor (ADORA2A), can contrast several harmful mechanisms observed in pathological conditions of heavy metal challenge or low tissue perfusion, such as varicocele." (PMID 33525681, 2021).
Venous thrombosis (1 paper, 2019). Formation of a blood clot (thrombus) inside a vein, causing the obstruction of blood flow. "In summary, these data are the first to demonstrate the efficacy of an adenosine A2A receptor agonist against venous thrombosis." (PMID 31015489, 2019). "In summary, these data are the first to demonstrate the efficacy of adenosine A2A receptor agonists against APS-accelerated venous thrombosis, with agonists functioning almost identically to DNase administration in the electrolytic model." (PMID 31015489, 2019). "Like CGS21680, dipyridamole suppresses aPL Ab-mediated NETosis via the adenosine A2A receptor and mitigates venous thrombosis in mice." (PMID 31015489, 2019). "Furthermore, dipyridamole (an FDA-approved drug known to potentiate adenosine signaling) phenocopies adenosine A2A receptor agonism in terms of suppressing both NETosis and venous thrombosis." (PMID 31015489, 2019). "Here, we demonstrate that a specific adenosine A2A receptor agonist can attenuate APS IgG-mediated NETosis in vitro and venous thrombosis in mice." (PMID 31015489, 2019).
Ventriculomegaly (1 paper, 2009). An increase in size of the ventricular system of the brain. "Treatment with CPA, an agonist of the adenoinse A1 receptor, and CGS21680, an agonist of the adenosine A2A receptor, for 2 weeks caused ventriculomegaly in 37% of the agonist-treated rats (n = 27)." (PMID 19725982, 2009).
tumor (305 papers, 2011 to 2026). "Several inhibitory markers, including CD276, HAVCR2, CTLA4, PDCD1LG2, LAIR1, and ADORA2A, were significantly upregulated in the high-risk group (p < 0.05), suggesting an immunosuppressive tumor microenvironment." (PMID 40963600, 2025). "The combined activation of the inflammasome pathway, which leads to substantial MDSC recruitment, and CD38 activation, which reduces the sensitivity of tumor cells to IFN-γ through ADORA2a activation, may lead to a loss of therapeutic efficacy and uncontrolled tumor progression." (PMID 33467713, 2021). "In contrast, ADORA2A (Adenosine A2A receptor) primarily contributes to immune suppression in the tumour microenvironment." (PMID 40417221, 2025). "For example, activation of ADORA2A can increase intracellular cAMP levels, which inhibits the effector function and anti-tumor activity of T cells." (PMID 40243466, 2025). "The expression of PYGB was significantly correlated with ADORA2A, a gene integral to the adenosine signaling pathway, which is critical for immunosuppression within the tumor microenvironment." (PMID 40458414, 2025). "ADORA2A also plays a critical role in tumor immune escape; elevated levels of adenosine in the tumor microenvironment activate A2A receptors via the CD39/CD73 axis, promoting immune evasion." (PMID 40243466, 2025). "Our result showed that higher purine metabolism in tumor epithelial cells is strongly associated with markers of Treg activation (CCR8, FOXP3, and IL2RA) and levels of ADORA2A, encoding the well-known purine receptor A2AR, in Tregs." (PMID 39252976, 2024). "Using CRISPR/Cas9 to knock out the adenosine A2A receptor was found to enhance the anti-tumor effects of Her2-targeted CAR-T cells in breast cancer." (PMID 38816881, 2024). "Overexpression of DSCAM and ADORA2A in HNC has been correlated with tumor progression and a poorer prognosis, thereby identifying them as potential therapeutic targets." (PMID 39628997, 2024). "It has been established that adenosine, an immunosuppressive factor, activates the adenosine A2A receptor, inhibiting the activation of multiple immune cells and suppressing the anti-tumor immune response." (PMID 38816881, 2024). "Compared with TG collected from healthy controls, the mRNA level of Adora2a increased in those of tumor-bearing mice." (PMID 38886342, 2024). "The adenosine A2A receptor (A2AR) has been proposed as a target for immunotherapeutic development due to its participation in immunosuppression of the tumor microenvironment." (PMID 38837964, 2024). "Inhibition of the G protein-coupled receptor (GPCR) adenosine A2A receptor (A2AR) has been proposed as a strategy for preventing immunosuppression by extracellular adenosine in the tumor microenvironment." (PMID 38837964, 2024). "It has also been confirmed that ADORA2A acts as an intrinsic negative regulator in the procedure of NK cell maturation and the anti-tumor immune response." (PMID 37848933, 2023). "In the tumor microenvironment, the expression of ADORA2A affects the function, differentiation, and number of CD8+ T cells." (PMID 37627013, 2023). "Blocking the in vivo formation and function of eAdo (Adoi), using a combination of anti-CD73 antibody and an Adora2a inhibitor slowed tumor growth and reduced metastatic burden." (PMID 37553182, 2023). "ADORA2A contact with Adenosine limits anti-tumor immunity by suppressing multiple immune subsets including T cells." (PMID 37945707, 2023). "Taken together, these data indicated that tumor cell-autocrine adenosine upregulates CCL5 secretion through the Adora2a–p38–STAT1 pathway." (PMID 37291128, 2023). "Similar to the in vivo results from the human NEPC cell line LASCPC-01, the xenograft tumor growth of the human SCLC cell line NCI-H146 was strongly inhibited by the ADORA2A inhibitor SCH." (PMID 38099497, 2023). "Tumor cell-derived eADO drives the recruitment of pDCs to tumors by interacting with the adenosine A2a receptor (A2AR) expressed on pDCs153." (PMID 37817484, 2023).
tumor (continued). "Compared to non-tumor gastric tissues and cell lines, ADORA2A expression was higher in gastric carcinoma (GC) tissues and cell lines." (PMID 37945707, 2023). "The expression of CLDN5 was strongly linked with that of immune checkpoint genes, such as TGFβ1, C10orf54, and ADORA2A in most tumor types, including STAD, COAD, and ESCA." (PMID 37286335, 2023). "With adenosine as a potential target, CTLA4-target CAR-T cells were engineered to express adenosine A2A receptor (A2AR) to suppress immune response and improve the anti-tumor effect." (PMID 35326556, 2022). "ADORA2A is an adenosine receptor, and blocking tumor-produced adenosine perhaps enhances the effect of immunotherapy." (PMID 36046241, 2022). "Adenosine is a metabolite produced abundantly in the tumor microenvironment, dampening immune response in inflamed tissues via adenosine A2A receptor (A2AR) which is widely expressed on immune cells, inhibiting anti-tumor immune response accordingly." (PMID 35899442, 2022). "Adenosine A2a receptor (A2AR) expressed on tumor cells inhibits the activation of immune cells and its expression is associated with cytokines such as HIF-1α." (PMID 36532071, 2022). "With increased tumor PD-L1, the expression of inhibitory checkpoint molecules (ICMs), including ADORA2A, BTLA, CD160, and PDCD1, was downregulated while the expression of IDO1 was upregulated." (PMID 33754038, 2021). "Adenosine is an immunosuppressive factor that limits anti-tumor immunity through the suppression of multiple immune subsets including T cells via activation of the adenosine A2A receptor (A2AR)." (PMID 34050151, 2021). "The results indicated that ADORA2A (P = 0.0076) and ADORA3 (P = 0.0142) receptors were significantly upregulated in BC tissues, reported being associated with tumor immune escape." (PMID 34220957, 2021). "After 21 days, the inhibition of ADORA2A with SCH-58261 significantly reduced tumor growth as well as the absolute number of TIL." (PMID 32146518, 2020). "Our experiments now add to this knowledge by demonstrating that the number of tumor-infiltrating B cells increases during the inhibition of ADORA2A." (PMID 32146518, 2020). "Of note, the inhibition of ADORA2A induced a significant decrease in the tumor mass even when the antagonistic therapy was started as late as one week after tumor initiation." (PMID 32146518, 2020). "At the same time, we observed an increased CD39+CD73+ co-expression, when murine tumor-infiltrating B cells were treated with the ADORA2A inhibitor SCH-58261." (PMID 32146518, 2020). "Human B cells express mostly ADORA2A with comparable expression levels in healthy volunteers and tumor patients." (PMID 32146518, 2020). "Other murine tumor studies have shown that the inhibition of ADORA2A decreases the number of T cells in the tumor environment and the metastasis of CD73+ tumors." (PMID 32146518, 2020). "Intriguingly, co-inhibition of adenosine signaling via CD73 and ADORA2A achieved better anti-tumor immune responses compared to single treatments, at least in pre-clinical models of breast and colon cancer." (PMID 31024543, 2019). "Adenosine and ADORA2A thus participate in shaping an immunosuppressive tumor microenvironment by negatively regulating CD8+ T cells." (PMID 31024543, 2019). "Antagonism of the adenosine A2A receptor on T cells blocks the hypoxia-adenosinergic pathway to promote tumor rejection." (PMID 29201461, 2017). "Adora2a on ECs promotes angiogenesis; its inhibition reduces tumor growth under hypoxia." (PMID 41346607, 2025). "ADORA2A regulates immune cells, such as T and dendritic cells, to facilitate tumour immune evasion." (PMID 40417221, 2025). "Additionally, animal studies have provided experimental evidence that Bifidobacterium pseudolongum enhances the recruitment of tumor-infiltrating lymphocytes (TILs) by ICI through the activation of the adenosine A2A receptor by the metabolite inosine." (PMID 40718835, 2025).
tumor (continued). "These discrepancies may also involve tissue-specific receptor dimerization: Adora2b-Adora2a heterodimers in ovarian cancer blunt pro-tumor effects, while Adora2b homodimers predominate in GC and breast cancer, amplifying signaling." (PMID 41346607, 2025). "Imaradenant is a novel potent and selective adenosine A2A receptor antagonist that is hypothesized to reduce immune suppression in the tumor microenvironment." (PMID 38086998, 2024). "Moreover, in an immunohistochemical study performed on 48 human PDAC tissues, Adora2a was overexpressed, and high Adora2a PDAC expression was associated with more aggressive cases and later tumor stages at the time of diagnosis." (PMID 37187740, 2023). "Extracellular adenosine triphosphate (ATP) is abundant in inflamed tumors, and its metabolite, adenosine (ADO), is a driver of immunosuppression mediated by adenosine A2A receptors (A2AR) and adenosine A2B receptors (A2BR) found on tumor-associated lymphoid and myeloid cells." (PMID 38263981, 2023). "As the end product of CD39-CD73 axis, adenosine mediates immunosuppression within the tumor microenvironment (TME) through triggering adenosine receptors on the membrane surface, including A1R (encoded by ADORA1), A2AR (encoded by ADORA2A), A2BR (encoded by ADORA2B), and A3R (encoded by ADORA3)." (PMID 36189223, 2022). "The subsequent engagement of adenosine with the adenosine A2A receptor (A2AR), expressed on DCs and effectors T cells, could robustly play against anti-tumor immunity." (PMID 34078376, 2021). "BET bromodomain inhibition also down-modulated expression of the A2A receptor (ADORA2A); this receptor and others in the extracellular adenosine pathway may play a role in maintaining a suppressive tumor microenvironment." (PMID 31653272, 2019). "Interestingly, caffeine acts as a natural inhibitor of ADORA2a and reduced tumor growth in a murine 3-MCA and melanoma model." (PMID 29464038, 2018). "Additionally, positive correlations with TGFB1 and ADORA2A highlight a highly immunosuppressive tumor microenvironment that could further inhibit effective anti-tumor responses." (PMID 41293172, 2025). "To test this hypothesis, we applied the ADORA2A-inhibitor SCH-58261 in our tumor-bearing mice." (PMID 32146518, 2020). "While ADORA2A’s role in immune evasion and suppression is important, THE ADENOSINE A1 RECEPTOR holds more potential for directly combating tumour progression, making it an ideal target for cancer therapy." (PMID 40417221, 2025). "Adenosine interacts with the adenosine A2A receptor (A2AR), decreasing the expression of adhesion molecules on endothelial cells and impairing the ability of CTLs to bind and migrate through the tumor vasculature." (PMID 39940924, 2025). "• Pan-cancer heterogeneity of CD39, CD73, and ADORA2A, ADORA2B.• Varying concentrations of eAdo in time and space.• eAdo level varies across tumor types." (PMID 41583489, 2025). "According to this study, PTK6 expression was positively correlated with CD160, IL10RB, and PVRL2 while being negatively correlated with ADORA2A, BTLA, CSF1R, and KDR in the other tumor types." (PMID 38573548, 2024). "5′-nucleotidase CD73 on NK cells, tumor cells, and other cells within the TME converts AMP to adenosine, which binds to the Adenosine A2A receptor (A2AR) and suppresses the function of NK cells." (PMID 40007761, 2024). "In support of these results, an inverse correlation between the staining intensity of ADORA2A and a typical AR target, PSA, was identified in human PCa tumor sections." (PMID 38099497, 2023).
tumor (continued). "Here the authors report the characterization of an adenosine A2A receptor (A2AR) eGFP reporter mouse, providing immunological insights into the biology of A2AR expression in the context of anti-tumor immunity." (PMID 37914685, 2023). "In the tumor microenvironment (TME), ADORA2A promotes adenosine signal transduction, inhibits infiltration of CD8+ T cells and NK cells, and promotes tumor progression." (PMID 37020558, 2023). "Conversely, the upregulation of certain ligand–receptor interactions, such as ADORA2A–ENTPD1, CLEC2D–KLRB1, CD80–CTLA4, and CD86-CTLA4, is indicative of inhibitory regulation of T and B cells, implying a detrimental effect on tumor immunity." (PMID 38077321, 2023). "We ran a second mIHC panel to assess differences in protein levels of PD-L1, adenosine A2A receptor (A2AR), and NY-ESO-1 in CD8+ T cells and tumor cells in patients with a durable CBR versus nonresponders, before and after treatment." (PMID 35671108, 2022). "Others have previously shown that the inhibition of ADORA2A in mice leads to a delayed growth of HNSCC tumors and enhances the anti-tumor response of CD8+ T cells." (PMID 32146518, 2020). "CPI-444, an adenosine A2A receptor (A2AR) antagonist, restores immune function and is active in preclinical tumor models." (PMID 30400835, 2018). "Moreover, the GSH‐GPX4 axis is conducive to inducing the expansion, survival and anti‐tumour response of CD8+ T cells, which can be hindered by the adenosine A2A receptor (A2AR)." (PMID 40045458, 2025). "Here, we sought to determine whether an increase in extracellular succinate levels is able to induce HIF2α protein accumulation in physiological oxygen tensions and increase expression of ADORA2A, COX4I2 and NDUFA4L2 in the context of a tumor background." (PMID 35740651, 2022). "With respect to receptors/ligands, tumor-induced immune tolerance is mediated by changes in the expression of several inhibitory checkpoints including CTLA-4, PD-1, and its ligand (PD-L1), LAG-3, TIM-3 and its ligand (galectin-9), and adenosine A2a receptor (A2aR)." (PMID 32878115, 2020). "Interestingly, in contrast to the prominent NE tumor phenotype in DKO prostates, TKO prostates displayed an evident expression of luminal cell markers CK8 and AR and a downregulation of the NE marker SYP, supporting a function of ADORA2A in modulating PCa cellular plasticity." (PMID 38099497, 2023).